IL2 (interleukin 2)
Diseases named in the same sentence as IL2 in open-access papers (continued):
Sharing a sentence is not in itself a finding about the gene and the disease.
autoimmune disease (continued). "In this review, we discuss the role of IL-2 in the pathogenesis of autoimmune diseases." (PMID 25322151, 2014). "The role of IL2 in maintenance of the self-tolerance and its activity in the main nerve system may have an effect on autoimmune diseases such as MS." (PMID 24959373, 2014). "Finally, future perspectives for use of IL-2 in the treatment of autoimmune disease are also presented." (PMID 25322151, 2014). "Therefore, defining the “low-dose” range of IL-2 capable of correcting the imbalance between immune tolerance and autoimmunity appears to be essential for the treatment of autoimmune disorders." (PMID 25322151, 2014). "Additionally, genetic associations between different polymorphisms located within the IL2/IL21 region as well as within both IL2RA and IL2RB loci and several autoimmune diseases have also been reported." (PMID 23676143, 2013). "Thus, other factors in addition to IL2RA and PTPN2 genotype likely contribute to reduced response to IL-2 in these two autoimmune diseases." (PMID 24376757, 2013). "Since IL-2 plays a key role in maintaining tolerance, it follows that patients with autoimmune diseases may display defects in the IL-2/IL-2R signaling pathway." (PMID 24376757, 2013). "The non-obese diabetic (NOD) mouse model, a prototypic model of spontaneous autoimmunity, mimics many features of human T1 D. Using this model, the contribution of the IL-2-IL-2R pathway to the development of T1 D and other autoimmune disorders has been extensively studied." (PMID 21059266, 2010). "Here, we review these recent findings and explore the role of the Treg/IL-2 axis in the pathophysiology of organ-specific autoimmune disorders such as T1 D the functional potential of IL-2 and its possible implication as a therapeutic agent in the context of autoimmunity." (PMID 21059266, 2010). "However, similar to STAT4, other IBD susceptibility genes such as IL23R, IL2/IL21, STAT3, and PTPN2 are associated with other autoimmune diseases." (PMID 20454450, 2010). "Interleukin 2 is known to expand Th17 cells in some autoimmune diseases." (PMID 21188205, 2010). "Therefore, the balance between proinflammatory (IL-2, IFN-γ and TNF) and regulatory (IL-4, IL-10 and TGF-β) cytokines probably determines any predisposition to develop autoimmune disease." (PMID 16759382, 2006). "By exploring specific metabolic pathways and their interplay with immune function, our findings offer novel insights that could inform the clinical application of Ld-IL2 therapy and potentially pave the way for new therapeutic strategies in the management of autoimmune diseases." (PMID 39482484, 2024). "It is well-known that high-doses of IL-2 can activate effector T cells to promote autoimmunity, which could result in the occurrence of autoimmune diseases, while low-doses of IL-2 can promote the development of a function that serves to control immune responses and maintain self-tolerance." (PMID 35514982, 2022). "Furthermore, deficiency of genes encoding for IL-2, IL-2 receptor (CD25) or CTLA-4 are associated with autoimmune diseases, indicating that these Treg associated cytokines and molecules are important for the prevention of autoimmune disorders." (PMID 36173485, 2022). "Several genes within the IL-2/IL-2R pathway (e.g., IL2, IL2RA, IL2RB, and PTPN2) may influence an individual’s susceptibility to human autoimmune diseases, with evidence to suggest that these genes exert their effects by altering Treg cell frequency or function." (PMID 33916798, 2021). "The T helper 1 (TH1) cells secrete IFN-γ, TNF-α, IL-2, IL-8 and mediate cellular immunity, activate macrophages to kill intracellular pathogens, and play an important role in immune regulation in the induction of organ-specific autoimmune diseases and anti-infective immunity." (PMID 33639877, 2021).
autoimmune disease (continued). "In addition, the acceptance of severe toxicities and side effects associated with high-dose IL-2 therapy seemed not to be justifiable in non-malignant conditions such as autoimmune diseases." (PMID 33868284, 2021). "Our research also found that low levels of IL-2 are effective signals for Treg cell activation and proliferation; therefore, low-dose IL-2 can be used to stimulate Treg cell proliferation and restore immune tolerance during treatment of autoimmune diseases such as RA." (PMID 33013198, 2020). "For example, H3K27ac regions containing autoimmune-disease-prioritized variants were linked to the TSS of genes using HiChIP and shown to contain cell-type-specific interactions between the TSS of the IL2 gene and rs7664452 in Th17 cells and between rs2300604 and target gene BATF in memory T cells." (PMID 31937202, 2020). "Therefore, the basis for using a low dose of IL-2 as a therapeutic for autoimmune disease was hypothesized." (PMID 32977677, 2020). "In addition, low-dose IL-2 can restore the balance between Treg and effector T cells in autoimmune diseases, which may be another reason why the level of IL-2 in group 3 went up." (PMID 33408682, 2020). "Moreover, stimulation of PD-1 with specific agonists, perhaps in combination with low-dose IL-2, could be an effective therapeutic strategy in autoimmune disease and in other immune disorders." (PMID 31781109, 2019). "Radiolabelled IL2 was extensively studied in animal models and patients with diabetes, in order to research T lymphocyte infiltrates in rats’ renal allografts, in Crohn’s and coeliac disease patients, in other autoimmune disorders and for imaging of vulnerable atherosclerotic plaques." (PMID 31091813, 2019). "Therefore, low-dose IL-2 therapies, which allow to expand Tregs while avoiding IL-2-induced clonal expansion or activation of T effector cells, are currently under clinical investigation for the treatment of autoimmune diseases." (PMID 31920671, 2019). "Similarly, autoimmune disease development is linked to IL-2 deficiencies in humans, most likely due to the expansion of immature non-functional Treg in the absence of IL-2 signals." (PMID 29527328, 2018). "Besides the anti-cancer actions of IL-2, augmentingin vivo T cell exposure to IL-2 might be beneficial in vaccine strategies or in efforts to treat autoimmune disease." (PMID 29123649, 2017). "Indeed, autoimmune diseases can be induced by IL-2 neutralization or defective IL-2 production." (PMID 27656181, 2016). "Thus, in order to maximize the ability of IL-2 to selectively enhance Treg function, a series of mouse and human studies have been undertaken to examine IL-2 dosing as a means to shift the balance between immunity and tolerance in autoimmune diseases." (PMID 26834735, 2015). "In theory, patients with other autoimmune diseases could also use IL-2 topical cream for treatment." (PMID 26276522, 2015). "Additionally, we present up-to-date preclinical and clinical studies on low-dose IL-2-based therapy of autoimmune disorders, and focus special attention on suitable dosing and frequency of IL-2 administration in the treatment of autoimmune diseases to avoid inappropriate immune responses." (PMID 25322151, 2014). "Thus, chronic GVHD may mimic more of a syngeneic autoimmune disease scenario, where CsA and IL-2 combination therapy might be beneficial." (PMID 24658577, 2014). "Th1 cells secrete cytokines such as IL-2, IFN-γ, and TNF-α that function in cellular immunity and delayed hypersensitivity inflammatory responses, and play an important role in autoimmune diseases and host resistance to intracellular pathogen infections." (PMID 40804957, 2025). "MS is an autoimmune disease induced by autoreactive T lymphocytes that is characterized by an imbalance of pro-inflammatory cytokines, such as TNF, interferon γ (IFN-γ), IL-2 and lymphotoxin, and regulatory cytokines (e.g., IL-4 and IL-10)." (PMID 40076462, 2025).
autoimmune disease (continued). "By tackling these difficulties and leveraging the existing data, the use of low-dose IL-2 therapy has the potential to become a fundamental component in the treatment of SLE and other autoimmune disorders." (PMID 39371877, 2024). "Firstly, we detected IL-2, IL-4, IL-5, IL-13, IL-17A, IL-17F, IL-22, IFN-γ, and TNF-α in the plasma to exclude the influence of infection or autoimmune disorders, and the standard curves were verified." (PMID 38343544, 2024). "While this orthogonal IL-2 technology is currently undergoing clinical development in the field of oncology (NCT05665062), its therapeutic potential for autoimmune diseases warrants further investigation." (PMID 39697333, 2024). "Therefore, significantly lower amounts of recombinant IL-2 may be used in the treatment of autoimmune diseases such as post-CHIKV chronic arthritis compared to dosages used in cancer therapy; however, further trials are needed to clarify the optimal low dose in CHIKV arthritis." (PMID 38507338, 2024). "Collectively, these results offer insights into the effect of an engineered, CD25hi biased IL-2 molecule on the tissue adaptation of Tregs and support the therapeutic use of SAR’336 for the control of autoimmune diseases." (PMID 39704171, 2024). "The complex of IL-2/JES6 (IL-2 and JES6–1 mAb) can selectively expand Tregs for the suppression of autoimmune diseases in EAE." (PMID 38807592, 2024). "MS is an autoimmune disease induced by autoreactive T-lymphocytes that is characterized by an imbalance of pro-inflammatory cytokines, such as TNF-α, IFN-γ, IL-2 and lymphotoxin, and regulatory cytokines (e.g., IL-4 and IL-10)." (PMID 39596101, 2024). "Th1 cells secrete IL-2, IL-8, IFN-γ, TNF-α, and other cytokines, which mediate cellular immune responses and organ-specific autoimmune diseases." (PMID 38369554, 2024). "By tackling these obstacles and leveraging the existing data, the use of low-dose IL-2 therapy has the potential to become a fundamental component in the treatment of SLE and other autoimmune disorders." (PMID 39371877, 2024). "Investigational New Drug (IND) application of IL-2/SD-01 has been approved and a first-in-human clinical trial in SLE and other autoimmune diseases is ongoing." (PMID 38461332, 2024). "Data presented in this report support that Ikzf1 hyperlactylation inhibits IL-2 expression and then promotes TH17 differentiation, providing mechanistic explanation for posttranslational modification–regulated IL-2 expression in autoimmune diseases." (PMID 37851814, 2023). "Th1 cells are involved in the pathogenicity of organ-specific autoimmune diseases and express the cytokines interferon gamma (IFN γ), tumor necrosis factor alpha (TNFα) and interleukin 2 (IL-2) which promote inflammation." (PMID 35392117, 2022). "It is hypothesized that this may be the result of masking of the positive effects of IL-2 (e.g., on NK-cell expansion and functionality) by preferential regulatory T-cell (Treg) expansion, an effect known when administering (low dose) IL-2 to patients with autoimmune diseases." (PMID 33926057, 2021). "It has previously been shown that IL-2/JES6 immunocomplexes potently expand Treg cells in vivo and that they can be used for treatment of various autoimmune diseases." (PMID 34932467, 2021). "Low-dose IL-2 treatment has been shown to expand the Treg population in patients with SLE and is used in clinical trials for treatment of autoimmune diseases, including SLE, rheumatoid arthritis, and multiple sclerosis." (PMID 32897879, 2020). "Drugs for inhibition of IL-2 and TNF-α are used for autoimmune diseases like rheumatoid arthritis, Crohn’s disease, colitis ulcerosa, or psoriasis." (PMID 32747802, 2020). "Treatment of cynomolgus monkeys with low doses of this IL‐2 mutein protein allowed for a sustained 10‐ to 14‐fold increase in CD4+ and CD8+ Tregs, which opens up possibility for using IL‐2 therapy to treat autoimmune diseases." (PMID 32881301, 2020).
autoimmune disease (continued). "Recently, it was reported that IL-2 bound to a specific monoclonal anti-IL-2 antibody (JES6-1A12) expands CD4+ CD25+ Tregs and protects against various experimental autoimmune diseases as well as rejection of an allogeneic solid organ graft." (PMID 32351497, 2020). "In line with this assumption, we showed that also in T cells from patients with autoimmune diseases, PL led to reduced expression of the T cell activation markers CD69 and CD25 and diminished production of IFNγ and IL-2." (PMID 32595640, 2020). "Therefore, the dosage of systemic IL-2 administration in these studies may play an important role in promoting the T cell response against the tumor, since low dose IL-2 has been used to preferentially expand Treg cells to attenuate the progression of human autoimmune diseases." (PMID 31058083, 2019). "We found, for example, that Cluster 7 represents a set of genes annotated by terms related to autoimmune disease and pathogen response, and contains a number of genes that mediate tissue interactions with the immune system, including INFG, IL2, IL2RB, and FAS." (PMID 29176608, 2017). "Data from the literature show that CFLAR is also regulated by the IL-2 and MAPK pathway and that abnormal expression is related to some diseases, such as cancer and autoimmune diseases." (PMID 28719625, 2017). "Patients with autoimmune disease including SLE, T1D, or rheumatoid arthritis have defective expression and regulation of IL-2 and IL-2R resulting in dysregulated Treg function and impaired downstream signaling." (PMID 26793191, 2015). "In animal model of autoimmune diseases, such as RA, anti-inflammatory action of Th1 cytokines, including IFN-gamma and/or IL-2, has been recently demonstrated." (PMID 25145773, 2015). "CD40 engagement in both T or B cells leads to the production of cytokines, such as IL-12, IL-2, TNF-α, IFN-α, and CD80, developing an environment which is conducive to autoimmune diseases." (PMID 23533546, 2013). "The predominant presence of CD4+ T-cells, an increased transcription of interleukin 2 (IL–2) and interferon–γ (IFNG) and low IL–4 mRNA expression in ERU-affected eyes suggest that ERU is a Th1-like-lymphocyte-mediated autoimmune disease." (PMID 23977091, 2013). "This 480 kB block of linkage disequilibrium includes IL2 and IL21, which are both functional candidate loci for autoimmune diseases." (PMID 22065918, 2011). "However, radiolabelled IL2 has the advantage to show the highest specificity since targets a single cell population, namely CD25 + T-cells, involved in the pathogenesis of autoimmune disease and in cancer progression." (PMID 40590904, 2025). "TNF-α plays a key role in acute inflammation and autoimmune diseases, IFN-γ amplifies cell-mediated immunity by stimulating macrophages and natural killer cells, and IL-2 is central to immune regulation and homeostasis and is synthesized primarily by activated T cells." (PMID 41459048, 2025). "So high-dose IL-2 should be used with careful patient screening and treatment in malignant conditions, which is not justifiable and effective to applied in autoimmune diseases." (PMID 40337274, 2025). "The variable induction of CEACAM1 in Tregs by low-dose IL-2 was not resolved when considering each autoimmune disease separately." (PMID 40773294, 2025). "When IL-2 is lacking, Treg suppression is impaired, disrupting immune homeostasis and leading to autoimmune diseases like pancreatitis." (PMID 39958351, 2025). "Given that VEGFA, IL2, and MPO all play roles in autoimmune diseases, in this study, kaempferol has been shown to bind well with these molecules, which suggests a potential avenue for therapeutic interventions targeted at these molecular interactions in the context of vitiligo." (PMID 38659590, 2024).
autoimmune disease (continued). "Moreover, caffeine mediates immune suppression of proinflammatory cytokine production, including tumor necrosis factor‐alpha (TNF‐α), interleukin 2 (IL‐2), and interferon‐gamma (IFN‐γ), which are crucial for the onset and progression of autoimmune diseases." (PMID 38370073, 2024). "In therapeutic cancer trials, high-dose IL-2 (>50 Million International Units (MIU)/8 hours) stimulates Teffs to attack cancer cells, whereas in low-dose IL-2 therapy (<6 MIU/day) for autoimmune diseases, Tregs are stimulated." (PMID 38507338, 2024). "To date, no IL-2 mutein therapies have been approved for use in humans but many clinical trials are underway testing their efficacy in classic autoimmune diseases." (PMID 36399073, 2023). "Different Th cell subtypes secrete various inflammatory cytokines: Th1 cells secrete interferon-γ (IFN-γ), interleukin-2 (IL-2), and tumour necrosis factor-alpha (TNF-α); Th2 cells secrete IL-4 and IL-5; and Th17 cells (present in the autoimmune disease pathophysiology) secrete IL-17 and IL-23." (PMID 37891878, 2023). "Murine studies have shown that mice lacking components of the IL-2/IL-2R signaling axis develop autoimmune diseases, suggesting that IL-2 is critical in generating functional Tregs." (PMID 36675037, 2023). "In autoimmune disease, KAT2A could catalyze histone H3 lysine H9 acetylation to induce the IL2 expression and modulate T cell immunity." (PMID 37415153, 2023). "However, low-dose IL-2 preferentially targets Treg cells with high CD25 expression, providing a favorable window for IL-2 treatment in autoimmune disease." (PMID 35296082, 2022). "Lack of IL-2 or their different receptor chains produces T cell hyperactivation and the development of various autoimmune disorders." (PMID 34869064, 2021). "Based on current results, low-dose IL-2, rather than anti-IL-2 agents, shows great promise for the treatment of autoimmune diseases." (PMID 33816637, 2021). "Low-dose IL-2 therapy emerged as a promising new therapy to treat a wide range of inflammatory and autoimmune disorders, but the effect of this therapy to infections has not been systemically evaluated." (PMID 34618873, 2021). "Low-dose IL-2 increases the number of Tregs; it has clinically used for the treatment of lupus and lupus nephritis and is currently being tested in AIH and other autoimmune diseases." (PMID 34208308, 2021). "At least, IL-2, IL-6, TNF-α, IFN-γ were produced when co-cultures of CII-CAR-T cells and fresh cartilage, and these cytokines also play roles in the occurrence and development of inflammatory arthritis and other autoimmune diseases." (PMID 33343563, 2020). "Furthermore, in T cells from patients with different autoimmune diseases PL inhibits the expression of the T cell activation markers CD69 and CD25 as well as production of IFNγ and IL-2." (PMID 32595640, 2020). "Moreover, low-dose IL-2 has been used to treat systemic lupus erythematosus (SLE), type 1 diabetes (T1D), and other autoimmune diseases and has shown some efficacy." (PMID 33013198, 2020). "In the absence of IL-2, Treg cells diminish greatly in number and function while Th17 cells expand to increase the potential for autoimmune disease and inflammatory disorders to develop." (PMID 31554863, 2019). "Treatment with F5111.2-human IL-2 complexes was effective in preclinical models of autoimmune diseases and GvHD, and it did not affect immune response to mouse CMV." (PMID 31921162, 2019). "Several additional clinical trials evaluating ld-IL-2 in multiple autoimmune and inflammatory diseases are ongoing, including TRANSREG (NCT01988506), which includes patients suffering from 1 of 11 selected autoimmune diseases." (PMID 29615964, 2018). "Interleukin-2 (IL-2) is critical for maintaining the function of the CD4+ regulatory T cells (Tregs), which in turn regulate autoreactive CD4+ effector T cells (Teffs) to prevent autoimmune diseases, such as T1D." (PMID 29867762, 2018).